SSX4B (SSX family member 4B)
Description:
Could act as a modulator of transcription.
Synonyms: CT5.4; OTTHUMT00000056510
Gene: Protein-coding gene on chromosome X (48,402,082 to 48,411,960, reverse strand). Ensembl gene ENSG00000269791.
Subcellular location (Human Protein Atlas): Nucleoli; Nucleoplasm
Gene Ontology:
Molecular function: protein binding
Biological process: regulation of DNA-templated transcription
Cellular component: nucleus
Homologues: Orthologues: chimpanzee SSX3 (97% identical), macaque SSX7 (84% identical), mouse Ssxb9 (32% identical), mouse Ssxb8 (31% identical), mouse Ssxb1 (31% identical), mouse Ssxb15 (31% identical), mouse Ssxb6 (31% identical), rat Ssx1 (31% identical), mouse Ssxb10 (30% identical), mouse Ssxb5 (30% identical), mouse Ssxb14 (30% identical), mouse Ssxb3 (30% identical), and 5 more. Paralogues in human: SSX4 (100% identical), SSX7 (82% identical), SSX3 (81% identical), SSX1 (79% identical), SSX2 (79% identical), SSX2B (79% identical), SSX5 (78% identical).
Diseases named in the same sentence as SSX4B in open-access papers:
SSX4B is named in the same sentence as 2 diseases in open-access papers, as found by Europe PMC text mining. Sharing a sentence is not in itself a finding about the gene and the disease. The quoted sentences say what the papers report.
melanoma (1 paper, 2016). A malignant, usually aggressive tumor composed of atypical, neoplastic melanocytes. "Furthermore, members of the synovial sarcoma X breakpoint family (SSX) (melanoma growth promoters) were also down-regulated (e.g. SSX2, SSX4, and SSX4B) as a result of miR-4731 overexpression." (PMID 27331623, 2016).
synovial sarcoma (1 paper, 2016). "The last segment is on chromosome X [coordinates 48,000,001–48,500,000], with three known genes belonging to the family of highly homologous synovial sarcoma X (SSX) breakpoint proteins showed expression values within the higher 2.5th percentile: SSX1, SSX4 and SSX4B." (PMID 27611585, 2016).